UVRAG (UV radiation resistance associated)
Diseases named in the same sentence as UVRAG in open-access papers (continued):
Sharing a sentence is not in itself a finding about the gene and the disease.
multiple sclerosis (1 paper, 2017). A progressive autoimmune disorder affecting the central nervous system resulting in demyelination. "Gene regions spanning the identified four-SNP signature, HLA-DQB2, MBP, UVRAG, and ZAK(CDCA7), are known to be related to either the MoA of Copaxone or the pathophysiology of multiple sclerosis: HLA-DQB2 is involved in antigen processing and presentation, central to Copaxone’s MoA." (PMID 28569182, 2017).
pancreatic adenocarcinoma (1 paper, 2024). "Furthermore, like SOCS3, it is considered a possible marker of radiosensitivity in pancreatic adenocarcinoma, transcriptionally suppressing the UV radiation resistance-associated gene (UVRAG) and modulating apoptosis, DNA repair, and autophagy." (PMID 39202425, 2024).
systemic lupus erythematosus (1 paper, 2021). An autoimmune multi-organ disease typically associated with vasculopathy and autoantibody production. "Cao's study showed that miR-125b-5p participates in the development of systemic lupus erythematosus and inhibits autophagy by targeting UVRAG." (PMID 33791049, 2021).
tumor (40 papers, 2010 to 2025). "UVRAG (UV radiation resistance-associated gene) is an important autophagy inducer and tumor suppressor." (PMID 38485957, 2024). "The ultraviolet radiation resistance-associated gene (UVRAG) plays a role in autophagy and has been implicated in tumor progression and prognosis." (PMID 37173968, 2023). "UVRAG has been generally accepted as a tumor suppressor in cancer, while in the present study, higher UVRAG expression was found to be negatively associated with the prognosis of CRC patients." (PMID 37173968, 2023). "We demonstrate that WDR6 promotes HCC progression by enhancing ubiquitination‐dependent degradation of tumor suppressor UV radiation resistance‐associated gene (UVRAG), thereby fostering an immunosuppressive and prometastatic tumor microenvironment." (PMID 36947051, 2023). "Recently, the role of Beclin1 and UV radiation resistance-associated gene (UVRAG) as a tumor suppressor and autophagy trigger in cancer was emphasized." (PMID 38239705, 2023). "Overexpression of UVRAG activates autophagy and suppresses tumor growth, whereas silencing of UVRAG causes failure of autophagy and uncontrolled cell proliferation." (PMID 31831743, 2019). "Mechanistic studies have indicated that the UV radiation resistance-associated gene (UVRAG), a tumor suppressor involved in autophagy, is recruited to UV-damaged foci and thus activates the photo lesion repair mechanism." (PMID 27941683, 2016). "Recent studies have shown that UVRAG, a key autophagic tumour suppressor, is mutated in common human cancers." (PMID 26234763, 2015). "Collectively, these results indicate that the frameshift UVRAG mutation is likely selected and is expressed as a truncated UVRAG protein in MSI tumours." (PMID 26234763, 2015). "Notably, single deletions or mutations of UVRAG, along with reduced expression of Bif-1 have been observed in BC, potentially impairing autophagy-mediated tumor suppression." (PMID 40688079, 2025). "The association between UVRAG expression and tumor immunity was explored and its mechanism was clarified, providing evidence for UVRAG as a potential therapeutic target, while the efficacy of UVRAG inhibition and combined regimens should be assessed in future studies." (PMID 37173968, 2023). "Moreover, various proteins associated with autophagy that directly suppress tumour development include Beclin-1, UVRAG, and Bif-1, as well as components that destroy proteins associated with tumour growth such as p62/SQSTM1." (PMID 34445354, 2021). "UVRAG, a key autophagy tumor suppressor, produces truncated mutations when CRC patients have MSI." (PMID 33937013, 2021). "The discoveries of UVRAG mutations in colorectal cancer cells, and that its overexpression increases autophagy and suppresses the proliferation of certain cancer cell lines, altogether suggest that this gene functions as an autophagic tumor suppressor." (PMID 26921396, 2016). "IL-4 activated M2 macrophages by c-Jun N-terminal kinase-signal transducer and activator of transcription (JNK-STAT) pathway and impaired DC functions, indicating that higher expression of UVRAG in epithelial cells was correlated with tumor immune escape." (PMID 37173968, 2023). "We found that UVRAG, which was identified as a tumor suppressor, was up-regulated 13.7-fold in long-lived M. myotis compared to M. molossus." (PMID 32674072, 2020). "One of them is autophagic tumor suppressor UVRAG, which is required for the dynamic integrity and pigmentation of melanosomes." (PMID 33318297, 2020). "UVRAG is a tumor suppressor candidate involved in autophagy, which is truncated in cancers by a frameshift (FS) mutation and expressed as a shortened UVRAGFS." (PMID 31831743, 2019). "UVRAG is involved in autophagy, which loses its tumour suppressor functions when in its truncated form in cancers." (PMID 31831743, 2019).
tumor (continued). "Many key autophagy-related proteins, such as Beclin 1, UV radiation resistance-associated gene (UVRAG), Bax interacting factor-1 (Bif-1), and autophagy-related (ATG), act as tumor suppressors, as their depletion leads to the development of cancer." (PMID 31284458, 2019). "In contrast, the level of UVRAG mRNA was significantly lower in tumor tissues than that in normal tissues." (PMID 26717041, 2016). "In cancer cell lines, overexpression of UVRAG is found to promote autophagy and reduce cell proliferation, raising the possibility that its tumor suppressor function involves the regulation of autophagy." (PMID 26921396, 2016). "UVRAG is a tumor suppressor, and as a component of PI3K (III) complex II, it has been suggested to regulate autophagy and vesicle trafficking in mammalian cells." (PMID 25006588, 2014). "While the role of Beclin 1 and UVRAG in DNA damage has been studied in the setting of tumorigenesis, little is known about the molecular details of their role in tumor cell response to cancer therapy." (PMID 24956373, 2014). "Beclin 1 and UVRAG function as tumor suppressor genes, and Beclin 1+/− mice were shown to be tumor-prone." (PMID 24956373, 2014). "It is established that autophagy has a tumor-suppressor role and several autophagy gene products including Beclin1 and UVRAG are known to function as tumor suppressor proteins." (PMID 22666256, 2012). "Besides, autophagy promotes the regulation of tumor suppression by Beclin-1 through its interaction with UVRAG and Bax interaction factor-1 (Bif-1)." (PMID 40688079, 2025). "UVRAG inhibition may restrain tumor progression by not only reducing tumor malignancy but also changing the immune environment." (PMID 37173968, 2023). "Hypoxic tumour cell-derived exosomal miR-340-5p confers radioresistance in OSCC by targeting KLF10/UVRAG, suggesting that miR-340-5p could be a potential biomarker and therapeutic target for the enhancement of radiosensitivity in OSCC." (PMID 33485367, 2021). "UVRAG may play diverse roles as an oncogene or tumor suppressor in different types or environments of carcinoma." (PMID 34681622, 2021). "In addition, several autophagic proteins can directly suppress tumour formation (e.g. Beclin-1, UVRAG and Bif-1) and autophagy has been shown to degrade tumour promoting proteins as well (e.g. p62/SQSTM1)." (PMID 29225688, 2017). "Nonetheless, alteration of genes attributed to the initial autophagosomes formation, e.g. Beclin1 (Atg6), Atg5, Atg12, UVRAG (UV radiation resistance-associated gene) and MAP1LC3 (Microtubule-associated proteins 1A/1B light chain 3), has been linked to tumor development." (PMID 27058414, 2016). "While cells with defective autophagy are prone to genomic instability that contributes to tumorigenesis, it is unknown whether Beclin1 or UVRAG can regulate the DNA damage/repair response to cancer treatment in established tumor cells." (PMID 24956373, 2014). "Conversely, autophagy can also inhibit tumor growth via beclin 1, UVRAG, Bif and Atg." (PMID 24676394, 2014). "We thus decided to analyze whether the role of UVRAG as a tumor suppressor is evolutionarily conserved in the adult Drosophila intestine and to understand which of its diverse functions might be relevant in a setting similar to that during colorectal cancer development." (PMID 26921396, 2016). "Like Vps34, UVRAG depletion can also induce accumulation of cellular vacuoles (Fig. EV5G) and reduce tumor cell death induced by dHL-60 neutrophils." (PMID 38806658, 2024). "As an example, Beclin1 executes its function as a tumor suppressor through regulation by AMBRA1, Bif1, and UVRAG." (PMID 38239705, 2023). "Autophagy induction via SMURF1-mediatd activation of UVRAG was shown to functionally result in autophagic degradation of oncoprotein EGFR and, consequently, suppress HCC cell proliferation and tumor growth." (PMID 36918822, 2023). "In HCC, the ubiquitination of UVRAG by SMURF1 induces autophagy maturation and inhibits tumor growth." (PMID 34681622, 2021).
tumor (continued). "Taken together, SLC7A11 acted as a ceRNA for STX17, UVRAG, and RAB33B in 20, 12, and 12 different tumor types, respectively, and acted as a ceRNA for the three genes in 379 OC tissues and in 90 drug-resistant tissues." (PMID 34790572, 2021). "This study deepens the understanding of UVRAG from the aspect of tumor immunity and provides more evidence for UVRAG as a novel therapeutic target with or without being combined with immunotherapy or molecular inhibitors." (PMID 37173968, 2023). "UVRAG regulates BECN1 expression, suggesting that the interaction between UVRAG and BECN1 may be a condition for the tumor suppressive effect." (PMID 37168865, 2023). "In addition to losing the wild-type (WT) UVRAG functions, this nonsense mutant acts as a dominant-negative mutant and contributes to the oncogenesis and tumour metastasis of CRC, likely by antagonizing the activity of UVRAGWT as a tumour suppressor." (PMID 26234763, 2015). "Furthermore, HULC overexpression in vivo induced tumor formation, and reduced ATG7, LC3 expression, while inducing SQSTM1 expression; however, we found that HULC overexpression did not influence ATG5, ATG12, Beclin-1, VPS34, P150 or UVRAG expression." (PMID 29022892, 2017).
cancer (29 papers, 2013 to 2025). A tumor composed of atypical neoplastic, often pleomorphic cells that invade other tissues. "Several studies, including ours, have demonstrated that KLF10 transcriptionally suppresses the UV radiation resistance-associated gene (UVRAG) and modulates apoptosis, DNA repair, and autophagy in cancer cells." (PMID 37958386, 2023). "Mice that express the truncated form of UVRAG, which is observed in cancer, were deficient in starvation‐ and LPS‐induced autophagy, and enhanced inflammation in a colitis‐associated cancer model due to NLRP3 inflammasome activation." (PMID 32745353, 2020). "Furthermore, similar to Beclin 1, UVRAG is also thought to have tumor suppressor activity, as it is regularly monoallelically deleted or mutated in these cancers." (PMID 30397185, 2019). "Also, mutation of exon 8 of UV radiation resistance-associated gene (UVRAG) reduced autophagy and promoted these cancer types." (PMID 28320471, 2017). "Thus, UVRAG is a crucial autophagy regulator in vivo, and autophagy promotion may help prevent/treat inflammatory disease and cancer in susceptible individuals." (PMID 31831743, 2019). "UVRAG is regarded as a suppressor gene in diverse types of cancer due to its function of accelerating autophagy." (PMID 37173968, 2023). "Grb2 was previously shown to be activated by ALK for cancer cell transformation and to interact with UVRAG, a regulator of the early stages of autophagy and autophagosomal maturation." (PMID 33452442, 2021). "In this research, we have found that the genes engaged in the induction of autophagy ULK1 and UVRAG have the lowest expression levels in both cancer and normal tissue." (PMID 28035578, 2017). "KAT5/TIP60-driven lactylation of PIK3C3/VPS34 at lysine residues 356 and 781 enhances its interaction with BECN1, ATG14, and UVRAG, promoting autophagy that may contribute to cancer progression." (PMID 39979245, 2025). "In addition, allelic deletion of Beclin-1–interacting proteins, such as Bif-1 and UVRAG also occurs in various cancers, and changes in the expression of them can increase the incidence of spontaneous cancer by altering the autophagy pathway." (PMID 34512368, 2021). "The human UVRAG gene is located on chromosome 11q13, which is a chromosomal region that is closely correlated to organ rotation/heterotaxy syndromes and human cancers, such as colon, breast, and gastric cancer." (PMID 30397185, 2019). "As a bona fide genome guardian, UVRAG is an attractive target for cancer therapy." (PMID 29112132, 2017). "By analysis of The Cancer Genome Atlas database, the mRNA level of USP1 was positively correlated with ATG14, UVRAG, and PIK3C3 (VPS34)." (PMID 39814232, 2025). "The core proteins of the LAP PI3KC3 complex (VPS34, VPS15, BECN1, UVRAG, RUBCN) present potential targets for developing novel cancer therapies." (PMID 39941753, 2025). "While UVRAG has been studied in multiple types of cancer, its function in CRC has not yet been fully clarified." (PMID 37173968, 2023). "Moreover, UVRAG patrols centrosome stability and DSB repair activity through direct binding to DNA-PK in NHEJ, standard mechanisms involved in cancer progression prevention." (PMID 29112132, 2017). "Therefore, novel cancer therapeutics may target UVRAG either to increase interaction with Beclin 1 and/or Bif-1, to increase autophagy, and facilitate degradation of oncogenic molecules; or to inhibit the UVRAG-BAX interaction, releasing BAX and triggering apoptosis." (PMID 23840208, 2013). "Additionally, bax-interacting factor 1 (BIF-1) and UV radiation resistance-associated gene protein (UVRAG), which is related to Beclin1, was found to be absent or mutated in variety of cancer types." (PMID 35211417, 2022).
infection (9 papers, 2015 to 2025). The state of being infected such as from the introduction of a foreign agent such as serum, vaccine, antigenic substance or organism. "Our results indicate that after the infection autophagic genes [Beclin-1 (p ≤ 0.03), UVRAG (p ≤ 0.03), Atg5 (p ≤ 0.01), Atg12 (p ≤ 0.01) and Atg16L (p ≤ 0.03)] are upregulated in contrast to the control group." (PMID 39845048, 2024). "Hepatitis C virus (HCV) infection induces Rubicon expression and represses UVRAG expression at the early infection stage, thus transiently impairing the fusion of autophagosomes to lysosomes to increase autophagosome formation for viral RNA replication." (PMID 38534345, 2024). "Using quantitative real-time RT-PCR, we demonstrate that genes encoding for Atg5, LC3B, hVps34, UVRAG, and STX17 are significantly up-regulated 6 h post-infection." (PMID 27242971, 2016). "These fold increases were similar to what was observed in HCV-infected cells at 24 hours post-infection, which were approximately 1.6-fold and 1.5-fold for Rubicon and UVRAG, respectively." (PMID 25807108, 2015). "Furthermore, the percentage of EEA1- and Rab7-positive compartments containing GAS in Beclin 1 and UVRAG KO cells decreased significantly, compared to that in wild-type cells during infection." (PMID 30488027, 2018). "To test this possibility, we first conducted the siRNA knockdown experiment to determine whether the inhibition of UVRAG expression would prevent the maturation of autophagosomes at 48 hours post-infection." (PMID 25807108, 2015). "We found that after 2 hours of infection, most bacteria colocalized with RUBCN, UVRAG, NOX2 and LC3, which clearly suggests that bacterial uptake in macrophages involves LAP." (PMID 40395986, 2025). "Both infectious HIV and AT-2-inactivated HIV increased the transcription of ATG9B, UVRAG, and MCOLN1 suggesting activation of TFEB by HIV does not require productive infection." (PMID 26115100, 2015).
UVRAG also shares sentences with these, for which no sentence is quoted: vitiligo (2 papers); bladder cancer (1); esophageal squamous cell carcinoma (1); glioblastoma (1); inflammatory bowel disease (1); ischemic stroke (1); leukemia (1); lung carcinoma (1); microcephaly (1); Primary microcephaly (1); Sepsis (1); Stroke (1); xeroderma pigmentosum (1).